CXCL12 (C-X-C motif chemokine ligand 12)
Diseases named in the same sentence as CXCL12 in open-access papers (continued):
Sharing a sentence is not in itself a finding about the gene and the disease.
breast carcinoma (continued). "The results of this study suggest that CB2-specific non-psychoactive synthetic cannabinoid JWH-015 inhibits CXCL12-induced migration and invasive properties of breast cancer cells." (PMID 21915267, 2011). "Moreover, as staining for CXCL12 and CCL21 (or CXCR4 and CCR7) was tightly linked in the group of primary tumors and lymph node metastasis tumors in this study, it is likely that a shared mechanism may account for variations in expression levels of both molecules in breast cancer." (PMID 20181250, 2010). "Breast cancer cells lacking expression of CXCL12 but exhibiting CXCR4 can metastasize to target organs that secrete CXCL12." (PMID 20830311, 2010). "The ability of wild-type CXCL12 to inhibit both primary tumor growth and metastasis makes it a more attractive candidate than the CXCR4 antagonist for incorporation into therapeutic strategies for breast cancer." (PMID 20849618, 2010). "In this work, we sought to determine whether a modified form of CXCL12, CXCL12(P2G), which acts as an antagonist of CXCR4, is able to block metastasis in the 4T1.2 orthotopic mouse model of breast cancer." (PMID 20849618, 2010). "Furthermore, CXCL12, the ligand for CXCR4, has been shown to be maximally expressed in the organs of metastasis in both lung and breast cancers." (PMID 19563666, 2009). "Stimulation of HDMECs with CXCL12 enhanced adhesion selectivity of circulating breast cancer cells by a comparable amount, regardless of expression of chemokine receptors CXCR4 or CXCR7 on cancer cells." (PMID 19484126, 2009). "CXCL12 functions through CXCR4 on endothelial cells to significantly enhance adhesion of circulating breast cancer cells, independent of CXCR4 or CXCR7 on cancer cells." (PMID 19484126, 2009). "Autocrine VEGF regulates the expression of the chemokine receptor CXCR4, which mediates the migration of breast carcinoma cells toward CXCL-12, required for tumor cells invasion but not for their survival." (PMID 19226458, 2009). "When added from the basal side, CXCL12 acts through receptor CXCR4 on endothelium to promote adhesion of circulating breast cancer cells, independent of CXCL12 receptors CXCR4 or CXCR7 on tumor cells." (PMID 19484126, 2009). "A role of the chemokine/receptor pair CXCL12/CXCR4, normally controlling cell trafficking within the marrow, in the development of solid tumour bone marrow metastases has been shown for small-cell lung cancer, breast cancer, and renal cell cancer." (PMID 18781150, 2008). "CXCL12 was reported to activate the migration of human melanoma and breast cancer cells that express CXCR4, ROBO1 and ROBO2, while SLIT2-ROBO interaction was demonstrated to inhibit chemotaxis, chemoinvasion and adhesion of breast cancer cells." (PMID 19114000, 2008). "Previous studies have shown that heparin is capable of antagonising chemokine function both in vitro and in vivo indicating its potential to disrupt the interaction between CXCL12 and CXCR4, thereby preventing the invasion of CXCR4 expressing breast cancer cells." (PMID 17726466, 2007). "The organ-specific spread of breast cancer cells to different sites, including the lymph nodes, has been reported in a mouse model to require the chemokine receptor CXCR4 on tumour cells and the chemokine CXCL12 in target organs." (PMID 16189523, 2005). "Still, using a more sensitive technique, we did not detect a difference in CXCR4 and CXCL12 expressions between primary breast carcinomas and matching lymph node metastases." (PMID 16189523, 2005). "Thus, CXCL12 and CXCL13/CXCR5 expression in the LNs of these breast cancer patients may be more relevant than other chemokines or receptors studied for LN involvement, resulting in a worse prognosis." (PMID 40584290, 2025).
breast carcinoma (continued). "Given the role of the CXCR4/CXCL12 axis in breast cancer metastatic spread, and the differences observed between MDA-MB-231 and MCF-7 cells, our data point to initial stages of breast cancer as possible models where targeting the CXCL12/HMGB1 heterocomplex could be particularly promising." (PMID 38803493, 2024). "Similarly, silencing the FHC gene increases ROS levels in breast cancer and lung cancer cells, activating the CXCR4/CXCL12 pathway, resulting in the acquisition of an epithelial-mesenchymal transition phenotype and promoting proliferation and migration ability." (PMID 38383702, 2024). "Interestingly, heightened CXCL12 expression levels could predict diminished overall survival (OS) and relapse-free survival (RFS) in patients across all breast cancer subtypes." (PMID 38001753, 2023). "This must necessarily lead to an organotropism; e.g., breast cancer cells express high levels of CXCR4 and CCR7, which are responsible for the metastasis formation in LN, lung, liver, and KM, as these organs are rich in corresponding ligands CXCL12 and CCL21 [Chambers3471]." (PMID 35326690, 2022). "The hypermethylation in the CXCL12 promoter region in more than 50% of breast tumors was detected by methylation-specific PCR, and the expressions of DNMT1 and DNMT3b were distinctly higher in CXCL12-methylated breast cancers than in CXCL12-unmethylated breast cancers." (PMID 35770088, 2022). "In breast cancer, some reports suggest that both receptors are found in the same cell, whereas others report that CXCR4 and ACKR3 are found in distinct cell subsets, with uptake of CXCL12 by ACKR3+ BC cells enhancing proliferation and metastatic potential of CXCR4+ cells." (PMID 36233192, 2022). "A functional interaction between the IGF1R and CXCR4 was documented in breast cancer cell lines where CXCR4 and IGF1R directly interacted at the cell membrane, thereby inducing IGF1-evoked CXCR4 transactivation and cell migration independently of its cognate ligand CXCL12." (PMID 34440844, 2021). "CXC motif chemokine receptor 4, the receptor for chemokine CXCL12/SDF-1 and a member of the G protein-coupled receptor superfamily, is overexpressed in various types of solid cancers, including non-small-cell lung cancer (NSCLC), breast cancer, colorectal cancer, and GC." (PMID 34568309, 2021). "Previous research has been reported that miR-130b-3p present in exosomes contributes to CXCL12/CXCR4-induced colorectal cancer metastasis into liver and downregulate PIEZO2, thereby activating the Hedgehog signaling pathway and leading to worsening breast cancer prognosis." (PMID 33612479, 2021). "Moreover, it is interesting to note that there is a difference between vasculature of breast cancer induced by either Her2+ where anti CXCL12 agents are not effective in contrast to Wnt1 derived tumors." (PMID 34445691, 2021). "In this review, we examine state-of-the-art knowledge about detrimental roles of the CXCL12/CXCR4 signaling, discuss its therapeutic potential and suggest further research directions beneficial both for basic research and personalized medicine in breast cancer." (PMID 33096815, 2020). "However, whether the CXCL12/CXCR4 and the HFG/c-MET axis hold similar significance in male breast cancer is unknown." (PMID 32188473, 2020). "The UALCAN analysis showed that only CXCL12 had a lower expression level in basal-like (triple-negative) breast cancer compared with luminal-like breast cancer, while CXCL5, IDO1, MIF, PTGS2, and VEGFA all had increased expression levels in basal-like breast cancer." (PMID 31293831, 2019). "Moreover, cats with CXCR4 positive PT exhibited significantly lower serum CXCL12 levels than cats with CXCR4 negative mammary carcinomas (p = 0.0324)." (PMID 30012106, 2018). "Finally, significant differences in OS (p = 0.0147) and DFS (p = 0.0279) rates were found between animals with HER2-overexpressing mammary carcinoma showing positive CXCL12 status and cats exhibiting negative CXCL12 expression." (PMID 30012106, 2018).
breast carcinoma (continued). "CXCL12 signaling may be connected to the phenotypic characteristics modified by COUP-TFI; thus, we hypothesized that COUP-TFI could target this signaling pathway in breast cancer cells." (PMID 24906407, 2014). "This signaling pathway, which is composed of the chemokine CXCL12 (also called SDF-1 for stromal cell-derived factor 1) and its receptors CXCR4 and CXCR7, play pivotal roles in the cell migration, angiogenesis, proliferation, and survival of many cancer cells, including breast cancer." (PMID 24906407, 2014). "In the setting of profound hypoxia and CXCR4 up-regulation in Treg, as occurs in basal-like breast cancer, CXCL12 may have a negative consequence of enhancing Treg recruitment and suppressing the anti-tumour immune response." (PMID 21521526, 2011). "To investigate whether the differential E2-regulation of CXCR4 and CXCR7 could be extended to other breast cancer cell lines, we analyzed the expression of the components of the CXCL12 axis in ER-positive ZR-75 and ER-negative MDA-MB-231 breast cancer cell lines." (PMID 21695171, 2011). "However, it is important to stress that the action of heparin in inhibiting breast cancer metastasis is potentially multifactorial, and not solely the result of the inhibition of CXCL12/heparan sulphate interactions." (PMID 17726466, 2007). "A series of in vitro experiments were performed to determine the shortest length of oligosaccharide capable of competing CXCL12 from a solid-phase of heparin or heparan sulphate matrix and inhibiting breast cancer cell migration, while exerting little or no anticoagulant effect." (PMID 17726466, 2007). "In basal-like breast cancer, the expression of chemokine CXCL12 and its receptor CXCR4 is increased significantly under hypoxic environment compared to other BC subtypes, which increases the degree of infiltration of CD4+T cell subsets with significant immunosuppressive effect, such as Tregs." (PMID 40438111, 2025). "Furthermore, to identify dynamic Clip170 tension variation during breast cancer migration and invasion, we transfected the cpstFRET-Clip170 probe into MCF7 and MDA-MB-231 cells, respectively, and established a short-term aggression model induced by CXCL12 stimuli." (PMID 36209218, 2022). "Blocking CXCR4 may attenuate breast cancer metastasis to regional lymph nodes and the lungs, and activation of CXCR4 is believed to be primarily ligand-dependent, as is supported by the antitumor efficacy of AMD 3100, an antagonist of chemokine (C-X-C motif) ligand 12 (CXCL12) binding." (PMID 22242160, 2012). "Src activation in response to CXCL12 and IGF1, potentiates PI3K/AKT activation, and aids survival of latent breast cancer DTCs independent of their hormone receptor status or cancer subtype." (PMID 31447846, 2019). "To date, reports on CXCL12 and CXCR4 expression in the Indonesian population have only come from studies of patients with breast cancer, but not yet from patients with CRC." (PMID 29887884, 2018). "CXCL12 was found to be increased in six of eight of the CAF samples, similar to findings in breast cancer stroma (data not shown) 40,41." (PMID 20812209, 2011). "Unlike CXCL12, however, CC chemokine ligand-21 (CCL21) - the ligand for CC chemokine receptor-7 (CCR7) - is highly expressed in the lymph nodes of breast cancer patients." (PMID 20181250, 2010). "In addition, in a previous study, the expression profiles of CXCL12/CXCR4/CXCR7 and CXCL13/CXCR5 in the positive and negative LNs of breast cancer patients were found." (PMID 40584290, 2025). "First, we verified that CXCL12wt, CXCL12-L29C, CXCL12M, and CXCL12D, but not CXCL4-S26C or CXCL12wt mixed with the specific CXCR4 inhibitor AMD3100 led to the increase of cytoplasmic Ca2+ in MDA-MB-231 breast cancer cells." (PMID 36229490, 2022).
breast carcinoma (continued). "It is not known whether CXCL12 and MIF are increased in lungs of irradiated breast cancer patients but future research could investigate the sputum, serum or urine of breast cancer patients in the acute or long-term response to radiation." (PMID 26396176, 2015). "One hypothesis is that these molecules occupy an allosteric site within CXCR4 not previously identified which does not interfere with CXCL12 or M1 signaling, but which may be partially required by CXCR4 and some as yet unidentified ligand to signal the intracellular milieu in breast cancer cells." (PMID 29682200, 2018).
prostate carcinoma (189 papers, 2006 to 2025). A carcinoma that arises from epithelial cells of the prostate gland. "High CXCR4 expression in prostate cancer cells is associated with their propensity to metastasize to the bone, a tissue that expresses a high level of the chemokine CXCL12." (PMID 36863017, 2023). "Consistently, loss of PTEN in prostate cancer cells enhances the AKT-mediated expression of CXCL12 and CXCR4." (PMID 34064589, 2021). "CXCL12 mediates the homing of cells that express CXCR4, and high levels of CXCL12 are associated with the preferential metastasis of prostate-cancer cells to the bone." (PMID 25884570, 2015). "CXCL12 and its receptors have been strongly linked to prostate cancer bone metastasis and are markers for poor prognosis." (PMID 23902739, 2013). "Taken together, these data define a relationship between PTEN loss and CXCL12/CXCR4 signaling in prostate cancer progression." (PMID 23902739, 2013). "Expression of CXCR4 is linked to the tendency of prostate cancer cells to metastasize to the bone, a tissue that expresses a high level of the chemokine CXCL12." (PMID 22359577, 2012). "Prostate cancer chemoresistance is associated with ASCs releasing CXCL12." (PMID 40076892, 2025). "Upon the combined treatment of docetaxel and ADT, prostate cancer cells can recruit and induce the polarization of the tumor-associated macrophages to release CXCL12, which in turn promotes the survival of cancer cells via CXCR4 and mediate the drug resistance." (PMID 34069563, 2021). "Clinical sample analysis revealed that CXCL12 expression by peritumoral adipose stroma is increased in obesity, and that the correlating increase in Pdgfr/CXCL12 expression in the tumor is linked with decreased survival of patients with prostate carcinoma." (PMID 33753872, 2021). "In fact, CXCL12 has been implicated in enhancement of prostate cancer cell metastasis to the bone." (PMID 32585812, 2020). "In a model of prostate cancer bone metastasis, CXCL12 expression was increased in the bone with the strongest staining observed within the endosteal region associated with osteoblasts, similar to osteoblast-derived CXCL12 in HSC homing." (PMID 29642534, 2018). "Moreover, tumor-derived IL-8 amplified stroma-derived CCL2-stimulated proliferation and promoted CXCL12-mediated invasion of PTEN-deficient prostate cancer cells." (PMID 28783760, 2017). "In prostate cancer, TDEVs increase CXCL12 production in bone marrow stromal cells (BMSCs) by transmitting PKM2, creating a microenvironment conducive to tumor cell engraftment." (PMID 41459253, 2025). "Inhibition of CXCL12/CXCR4 pathway has been shown to reduce the incidence of bone metastasis in prostate cancer." (PMID 41347146, 2025). "CXCL12 is a chemokine secreted by stromal and pro-inflammatory macrophages in prostate cancer that binds CXCR4 on lymphocytes, tumor cells, and myeloid populations to guide their migration." (PMID 41228234, 2025). "Therapeutic blockade of the CXCL12/CXCR4 axis with CXCR4 inhibitors in prostate cancer models reduces Treg infiltration, restores CD8+; cytotoxicity, and suppresses tumor growth, with the strongest effects seen when combined with IL-2 supplementation." (PMID 41228234, 2025). "In a myc-induced obesity-driven mouse model of prostate cancer, immunofluorescence staining of ventral prostate tissue shows high levels of CXCL12 in stromal compartments and high staining of CXCR4 and CXCR7 in tumor epithelial compartments." (PMID 41347146, 2025). "In prostate cancer, researchers find that CAFs secretes CXCL12 and CXCL14 to promote macrophage M2 polarization." (PMID 38827236, 2024).